PRSS1 (serine protease 1)
Diseases named in the same sentence as PRSS1 in open-access papers (continued):
Sharing a sentence is not in itself a finding about the gene and the disease.
ovarian carcinoma (7 papers, 2020 to 2025). A malignant neoplasm originating from the surface ovarian epithelium. "Some studies have reported the upregulation of PRSS1 in ovarian cancer and its association with platinum resistance." (PMID 40364249, 2025). "Thence, PRSS1 overexpression caused the decrease in Bax/Bcl-2 ratio, which halted the apoptosis of ovarian cancer cells." (PMID 33585454, 2020). "Although these findings primarily pertain to ovarian cancer, they suggest that PRSS1 may be implicated in chemoresistance mechanisms relevant to endometrial cancer therapy as well." (PMID 40364249, 2025). "Tissue Factor (TF)-FVIIa is known to induce PAR2 activation in ovarian cancer, so relative expression of TF or trypsin-1/2 (encoded by PRSS1/2), which accounts for the majority of trypsin isoforms, was compared between ovarian surface epithelium (OSE) and ovarian cancer tissues." (PMID 32365084, 2020). "In conclusion, we identified a novel risk gene PRSS1 related to ovarian cancer platinum response and confirmed its key roles using multiple levels of low-throughput experiments, revealing a new treatment strategy based on a novel target factor for overcoming cisplatin resistance in ovarian cancer." (PMID 33585454, 2020). "To investigate whether PRSS1 is associated with platinum response in ovarian cancer, we detected its differential expression in cisplatin-resistant/sensitive patients." (PMID 33585454, 2020). "The top 10 genes with most deleterious mutations in the Chinese ovarian cancer population were MC1R (12%), MLH1 (9%), PRKDC (8%), KIF1B (8%), FANCM (7%), FANCI (6%), PRSS1 (6%), SDHA (6%), BRCA2 (6%), and CFTR (5%)." (PMID 38817903, 2024). "PRSS1's expression pattern was continuously studied in Oncomine and cBio Cancer Genomic Portal databases, revealing the key roles of PRSS1 in ovarian cancer formation." (PMID 33585454, 2020). "To further study the biological function of PRSS1 in ovarian cancer, we conducted in vitro cytology tests on cisplatin-resistant cell lines A2780DDP and Skov3DDP and sensitive cell lines A2780 and Skov3." (PMID 33585454, 2020). "As verified by scientific low-throughput test, PRSS1 can be a potential biomarker for predicting platinum response in ovarian cancer." (PMID 33585454, 2020). "In Oncomine database, PRSS1 was more highly expressed in ovarian cancer tissues than in normal tissues." (PMID 33585454, 2020). "In the results of enrichment analysis, the pathway involving PRSS1 and its co-expression genes was closely related to platinum resistance in ovarian cancer." (PMID 33585454, 2020). "Hereafter, we conducted in-depth explorations on PRSS1's platinum response to ovarian cancer through tissue and cytological experiments." (PMID 33585454, 2020). "After the analysis, we focused on the top-ranked PRSS1 and explored its biological roles in ovarian cancer." (PMID 33585454, 2020). "By cell transfection assay, we observed that knockdown of PRSS1 reduced the resistance of ovarian cancer cells to cisplatin." (PMID 33585454, 2020). "Similarly, PRSS1, another PRSS3 protein family member, was reported to be negatively associated with the sensitivity of ovarian cancer cells to cetuximab, which functions by cleaving cetuximab thus leading to resistance." (PMID 36618965, 2022). "Moreover, knockdown of PRSS1 increased platinum sensitivity, and overexpression reduced platinum resistance in ovarian cancer." (PMID 33585454, 2020). "Therefore, knockdown of PRSS1 expression led to an increased ratio of Bax/Bcl-2, which promoted the apoptosis of ovarian cancer cells." (PMID 33585454, 2020). "However, other biological roles that are related to platinum response of PRSS1 in ovarian cancer, including invasion, angiogenesis, epithelial-mesenchymal transition, and cell survival, need to be further investigated." (PMID 33585454, 2020). "The results showed that knockdown of PRSS1 enhanced the sensitivity of ovarian cancer cells." (PMID 33585454, 2020).
ovarian carcinoma (continued). "Finally, the overexpression of PRSS1 weakened the sensitivity of ovarian cancer cells to platinum." (PMID 33585454, 2020). "Furthermore, the topmost ranked genes in CR doublets included PRSS1, ECE1 and UBE2C, which promote ovarian cancer chemoresistance and progression." (PMID 40280979, 2025).
diabetes (5 papers, 2006 to 2024). "The cumulative rates of pancreatic exocrine insufficiency and diabetes mellitus in both patients with PRSS1 and SPINK1 mutations were 16.1% and 5.5% at 20 years of age, and 45.3% and 28.2% at 40 years of age, respectively." (PMID 33375361, 2020). "In this study, we describe the glycemic pattern of five patients with diabetes secondary to a mutation in the PRSS1 gene, which leads to an increased autocatalytic conversion of trypsinogen to active trypsin, that results in autodigestion and damage to the acinar cells." (PMID 28101143, 2017).
breast carcinoma (4 papers, 2014 to 2022). "The genes PRSS1, TRPV5 and PIP have so far been implicated in a few cancer types (pancreatic-, non-small cell lung- and breast cancer), while EphB6 and TRPV6 have been studied in relation to numerous cancer types." (PMID 29299148, 2017).
cystic fibrosis (4 papers, 2021 to 2024). Autosomal recessive disorder caused by pathogenic variants in the CFTR gene (cystic fibrosis transmembrane conductance regulator), which encodes a chloride and bicarbonate channel expressed in epithelial cells, and follow the diagnosis criteria. "In particular, mutations that most commonly play a crucial role in the etiology of CP are associated with the PRSS1 (gene-encoding cationic trypsinogen), SPINK1 (Serine Protease Inhibitor Kazal type 1), CFTR (cystic fibrosis), CTRC, and CPA1 genes." (PMID 38978842, 2024). "These include hereditary pancreatitis induced by mutations in PRSS1, metabolic syndrome caused by mutations in CELA2A, Cystic Fibrosis, and Wolcott-Rallison Syndrome." (PMID 35769082, 2022).
gastric cancer (4 papers, 2020 to 2025). A primary or metastatic malignant neoplasm involving the stomach. "The involvement of alterations of the Prss1 gene has previously been associated with elevated gastric cancer risk and pediatric tumors including sarcomas." (PMID 33207594, 2020). "Nevertheless, silencing of PRSS1 has been reported to inhibit the extracellular signal-regulated kinase (ERK) signaling pathway by reducing PAR-2 activation, thereby suppressing the growth and proliferation of gastric carcinoma cells." (PMID 40382561, 2025).
Lynch syndrome (4 papers, 2020 to 2024). An autosomal dominant hereditary neoplastic syndrome characterized by the development of colorectal carcinoma and a high risk of developing endometrial carcinoma, gastric carcinoma, ovarian carcinoma, renal pelvis carcinoma, and small intestinal carcinoma. "No pathogenic variants were observed in BRCA1, STK11, CDKN2A, APC, PRSS1, or those genes associated with Lynch syndrome." (PMID 39594734, 2024).
CARASIL (3 papers, 2010 to 2022). CARASIL is a hereditary cerebral small vessel disease characterized by early-onset gait disturbances, premature scalp alopecia, ischemic stroke, acute mid to lower back pain and progressive cognitive disturbances leading to severe dementia. "Homozygous or compound heterozygous mutations in the high-temperature requirement A serine protease 1 gene (HTRA1) elicits cerebral autosomal recessive arteriopathy with subcortical infarcts and white matter lesions (CARASIL)." (PMID 36619910, 2022). "In a case report study, a homozygous variant of c.847G>T in the HtrA serine protease 1 (HTRA1) gene was found in a patient with symptoms of Cerebral autosomal recessive arteriopathy with subcortical infarcts and leukoencephalopathy (CARASIL) and WMHs in MRI." (PMID 33352859, 2020).
exocrine pancreatic insufficiency (3 papers, 2020 to 2024). Inability of the exocrine pancreas to produce and secrete an adequate amount of digestive enzymes into the small intestine. "It has been reported that the N29I mutation of Prss1 induces exocrine pancreatic insufficiency earlier than other mutations." (PMID 32547704, 2020).
gallstones (3 papers, 2015 to 2025). Solid crystalline precipitates in the biliary tract, usually formed in the gallbladder, resulting in the condition of cholelithiasis. "In this case, since there was no obvious gallstone or sludge demonstrated on imaging, the etiology of AP is primarily attributed to the PRSS1 gene mutation." (PMID 40230746, 2025).
autoimmune pancreatitis (2 papers, 2017). "Recently, we have demonstrated that PRSS1 mutations cause ectopic trypsinogen activation and thereby result in type 1 autoimmune pancreatitis (AIP)." (PMID 28151472, 2017). "After removing, seventy-three articles potentially met the inclusion criteria for eligibility, and 63 were excluded for the reasons as follows: not relevant (n = 46), no genotyping for PRSS1 (n = 7), no genotyping for p.R122H (n = 6), recurrent AP (n = 3), and autoimmune pancreatitis (n = 1)." (PMID 29118810, 2017).
dyslipidemia (2 papers, 2020 to 2025). "Mannan-binding lectin serine protease 1 (MASP1), which plays a role in the lectin pathway of the complement system, has been identified as a biomarker of prediabetes and is relevant to obesity, dyslipidemia and hypertension in cardio- and cerebrovascular patients." (PMID 32089734, 2020).
leukemia (2 papers, 2015 to 2025). A malignant (clonal) hematologic disorder, involving hematopoietic stem cells and characterized by the presence of primitive or atypical myeloid or lymphoid cells in the bone marrow and the blood. "Collectively, the findings of our study, together with all those previous reports, shed light on the potential complex in-context dependent role of PRSS1 in the development and progression of cancer generally, and leukemia particularly." (PMID 40382561, 2025).
lymph node metastasis (2 papers, 2020 to 2021). "In the present study, we confirmed that PRSS1 was highly expressed in GC, which was positively correlated with tumor differentiation, tumor size, TNM stage and lymph node metastasis of GC and was associated with poor prognosis." (PMID 33867821, 2021).
pancreatic adenocarcinoma (2 papers, 2020 to 2021). "At the level of germline variants, our results highlight a potential role for trypsinogen-regulating genes, including PRSS1 and SPINK1, in predisposition toward BTC, though the significantly increased risk for pancreatic adenocarcinoma associated with these two genes remains controversial 43,44." (PMID 33754015, 2021).
serous ovarian carcinoma (2 papers, 2022 to 2025). "In recent work, using immunostaining and fluorescent imaging, the authors revealed that the gene PRSS1 was overexpressed in the endoplasmic reticulum of a high-grade serous ovarian cancer cell line." (PMID 35053566, 2022).
acute leukemia (1 paper, 2025). A clonal (malignant) hematopoietic disorder with an acute onset, affecting the bone marrow and the peripheral blood. "In ROC analysis, PRSS1 showed good diagnostic value in acute leukemia patients and in ALL patients, and very good diagnostic value in AML patients, nominating it as a promising diagnostic biomarker for acute leukemias, especially AML." (PMID 40382561, 2025). "Both ADAM6 and PRSS1 exhibited a strong potential as novel diagnostic biomarkers for acute leukemia." (PMID 40382561, 2025). "Conclusively, the results of the current study portray ADAM6 and PRSS1 as potential novel diagnostic/prognostic biomarkers and therapeutic targets in acute leukemia." (PMID 40382561, 2025). "The results of the current study portray ADAM6 and PRSS1 as new potential diagnostic/prognostic biomarkers and potential therapeutic targets in adult acute leukemia patients, and shed light on their role as novel interrelated mediators possibly implicated in tumor micro-environment remodeling." (PMID 40382561, 2025). "This, at least partially, helps to explain the observed altered levels of PRSS1 in acute leukemia patients compared to healthy controls in our current study." (PMID 40382561, 2025). "Higher circulating ADAM6 and lower circulating PRSS1 levels were observed in acute leukemia patients compared to healthy control subjects." (PMID 40382561, 2025). "Serum levels of PRSS1 were found to be significantly negatively correlated with platelet count (r = − 0.353, p = 0.002) in acute leukemia patients." (PMID 40382561, 2025). "Further, in-depth thorough molecular studies are warranted to elucidate the mechanism of action of ADAM6 and PRSS1 in acute leukemia, and also to study their possible role and interrelation in other hematological malignancies and solid tumors." (PMID 40382561, 2025). "In the current study, we sought to determine the serum levels of ADAM6 and PRSS1, novel potential biomarkers with emerging implications in leukemogenesis, in adult patients with de novo acute leukemia compared to apparently healthy subjects." (PMID 40382561, 2025). "Interestingly, ADAM6 and PRSS1 were found to be significantly negatively correlated with each other in the whole study cohort, including controls and acute leukemia patients." (PMID 40382561, 2025). "Interestingly, ADAM6 serum levels were found to be significantly higher while PRSS1 serum levels were found to be significantly lower in acute leukemia patients compared to their control counterparts." (PMID 40382561, 2025). "However, the findings of the current study provide a proof-of-principle, opening the door for future large-scale clinical studies to further elucidate the role of ADAM6 and/or PRSS1 in acute leukemia, as well as other types of cancer." (PMID 40382561, 2025). "Additionally, the current study adopted a cross-sectional design in which the levels of ADAM6 and PRSS1 were measured in patients with acute leukemia and control subjects at one time point and cannot detect a cause-effect relationship." (PMID 40382561, 2025). "Furthermore, it’s important to point here that upon analysis of publicly available TARGET datasets for much larger cohorts of AML and ALL; ADAM6 and PRSS1 exhibited the same observed pattern of differential expression in acute leukemia patients compared to normal controls." (PMID 40382561, 2025). "In the whole study cohort, including control subjects and acute leukemia patients, Serum levels of ADAM6 were found to be significantly negatively correlated with serum levels of PRSS1 (r = −0.4264, p < 0.0001)." (PMID 40382561, 2025). "Also, future studies are warranted to investigate the possible interplay between PRSS1 and other ADAM family members in acute leukemia, as well as various cancer types." (PMID 40382561, 2025). "Furthermore, serum levels of PRSS1 exhibited a significant negative correlation with platelet count in acute leukemia, specifically in ALL." (PMID 40382561, 2025).
acute myeloid leukemia (1 paper, 2025). Acute myeloid leukemia (AML) is a group of neoplasms arising from precursor cells committed to the myeloid cell-line differentiation. "Thus, this study was designed to investigate the roles of ADAM6 and PRSS1 in ALL and acute myeloid leukemia (AML) in adults." (PMID 40382561, 2025).
Cachexia (1 paper, 2020). Severe weight loss, wasting of muscle, loss of appetite, and general debility related to a chronic disease. "Four were common for local/cachexia (C1R, PRKCG, ELANE, SOST: all oppositely regulated) and four for metastatic/cachexia (SERPINA6, PDGFRA, PRSS2, PRSS1: all consistently changed), suggesting that stage and cachexia status might be molecularly separable." (PMID 33334063, 2020).
cervical cancer (1 paper, 2021). A primary or metastatic malignant neoplasm involving the cervix. "Recent studies have shown that the PRSS1 protein is important in the development of pancreatic, colorectal and cervical cancer 7-9." (PMID 33867821, 2021).
cholangiocarcinoma (1 paper, 2024). A carcinoma that arises from the intrahepatic biliary tree (intrahepatic cholangiocarcinoma) or from the junction, or adjacent to the junction, of the right and left hepatic ducts (hilar cholangiocarcinoma). "We aimed to investigate the potential antitumor effect of upamostat and opaganib, individually and in combination, on CCA patient-derived xenografts (PDX) in nude mice using PAX165, a cholangiocarcinoma PDX that expresses substantial levels of SPHK2, PRSS1, PRSS2, and PRSS3." (PMID 38473407, 2024).
Cognitive impairment (1 paper, 2024). Abnormal cognition is characterized by deficits in thinking, reasoning, or remembering. "Utilizing various algorithms, we identified Cpa1 and Prss1 as potential key genes associated with the cognitive impairment caused by cadmium." (PMID 38287418, 2024).
colon cancer (1 paper, 2025). "The transcriptome, metabolome, and combined omics analysis showed that the changes in colon cancer organoids after inhibition of PHGDH were mainly involved in PRSS1 and PRSS56, steroid hormone biosynthesis, phenylalanine metabolism, ascorbate and aldarate metabolism, and tyrosine metabolism." (PMID 39670663, 2025).
colorectal cancer (1 paper, 2024). A primary or metastatic malignant neoplasm that affects the colon or rectum. "PRSS1 encodes pancreatic serine proteinase, trypsin-1 whose expression has been associated with the sensitivity to EGFR inhibitors of cetuximab in colorectal cancers, and its inhibition reduces the tumor growth." (PMID 39160568, 2024).
coronary artery disease (1 paper, 2021). "Manipulating GSK-3beta is a promising strategy for myocardial protection in coronary artery disease and heart failure.PRSS1 is mainly involved in proteolysis and digestion." (PMID 33628326, 2021).
endometriosis (1 paper, 2021). The growth of functional endometrial tissue in anatomic sites outside the uterine body. "Changes in cytokine concentrations in peritoneal and follicular fluids were discovered in patients with endometriosis, and a higher level of mannan-binding lectin serine protease 1 (MASP-1) was found both in patients with endometriosis and in patients with SLE6,28,29." (PMID 33436777, 2021).
Fever (1 paper, 2020). Body temperature elevated above the normal range. "For example, the proteins PRSS1 and PTGS2, targeted by quercetin, luteolin, and stigmasterol, are important in curing fever." (PMID 32811894, 2020).
glioblastoma (1 paper, 2022). The most malignant astrocytic tumor (WHO grade IV). "For examples, human PRSS1 (cationic trypsinogen) is one of the EV-A71 IRES-associated proteins in human glioblastoma T98G cells and the cleavage of hemagglutinin (HA) by activated human trypsinogen (PRSS3) enhanced influenza A virus infection." (PMID 35896602, 2022).
Hematuria (1 paper, 2021). The presence of blood in the urine. "Remarkably, we also found the expression of exosomal GAS5 was significantly negatively associated with the tumor grade and degrees of hematuria (all P < 0.05), whereas, the exosomal KLHDC7B, CASP14, PRSS1, and MIR205HG showed positive correlation with tumor grade and hematuria degrees." (PMID 33987102, 2021).
hereditary cancer (1 paper, 2021). Malignant neoplasms occurring in families at a rate greater than that expected by chance and caused by germline mutations in a specific gene. "Other segdup regions, including NEB (exons 83–103), PMS2 (exons 12–15), PRSS1, and SDHA, accounted for 358 additional findings within the hereditary cancer, neurology, and pediatric indications." (PMID 34007000, 2021).